IL6 (interleukin 6)
Diseases named in the same sentence as IL6 in open-access papers (continued):
Sharing a sentence is not in itself a finding about the gene and the disease.
atherosclerosis (continued). "Preclinical studies in murine models have shown that IL-6 promotes atherosclerosis and possibly plaque vulnerability and that injection of IL-6 results in increased CRP, TNF-α, and fibrinogen levels." (PMID 37629526, 2023). "IL6 is also a pro-inflammatory cytokine that plays a crucial role in inflammation, atherosclerosis, and thrombosis, and can influence the rate of lipid metabolism, specifically the metabolism of TCs and TGs48." (PMID 37076581, 2023). "Inthe previous several years, IL-1β and IL-6, two cytokines upstream fromCRP, emerged as key players in atherosclerosis." (PMID 39076864, 2023). "For atherosclerosis, the results from an animal model shows that IL-6 signaling contributed to the initiation of atherosclerosis and plaque destabilization in mice." (PMID 37113481, 2023). "A previous study linked TUG1 with inflammation as TUG1 knockdown decreased IL-6 and TNF in an animal model of atherosclerosis as well as upregulated inflammatory factor expression by sponging miR-133a in ox-LDL-treated macrophages." (PMID 37736902, 2023). "IL-6 which is secreted from mononuclear macrophages has moderate inflammatory activity and is highly related to atherosclerosis and its development." (PMID 37427329, 2023). "The anti-inflammatory cytokines that were upregulated in AAA at 7, 14, and 28 days include IL-6, Il-2, IL-11, and IL-10; however, the anti-inflammatory cytokines that were upregulated in atherosclerosis include IL-6 and IL-2." (PMID 38327764, 2023). "Blood IL-6 levels are associated with CVD as including endothelial dysfunction, arterial stiffness and atherosclerosis." (PMID 38017432, 2023). "Polymorphisms in inflammatory cytokine genes, like interleukin-6 (IL-6) and tumor necrosis factor-alpha (TNF-α), modulate inflammatory responses, promoting atherosclerosis progression." (PMID 37868550, 2023). "On the one hand, IL-6, typically following IL-1 stimulation, ignites inflammation in atherosclerosis." (PMID 36834808, 2023). "A double‐blind, randomized, placebo‐controlled, phase 2 trial also showed that IL‐6 inhibition with ziltivekimab markedly reduced biomarkers of inflammation and thrombosis relevant to atherosclerosis in patients with advanced chronic renal disease." (PMID 37287421, 2023). "For example, IL-6 has been rapidly gaining attention as a key targeted by the atherosclerosis research community." (PMID 37485268, 2023). "Among thousands of cytokines, NOD-, LRR-, and pyrin domain-containing protein 3 (NLRP3), C-reactive protein (CRP), IL-1, and IL-6 were involved in atherosclerosis pathogenesis." (PMID 37555019, 2023). "IL-6 is recognized as an upstream inflammatory cytokine and accelerate the downstream inflammation toward atherosclerosis." (PMID 37104297, 2023). "IL-6, a multifunctional cytokine, plays a key role in the development of cardiovascular diseases, such as hypertension, atherosclerosis, and kidney diseases." (PMID 37920615, 2023). "Animal models showed that trans-signaling of IL-6 and gp130 aggravates atherosclerosis and contributes to plaque rupture." (PMID 37600028, 2023). "Additional studies have shown that liraglutide and exenatide decrease the levels of IL-1β, IL-6, TNF-α, and CRP, and the risk of atherosclerosis formation." (PMID 37175496, 2023). "Several cytokine blockers have shown favorable results in atherosclerosis, including IL-1 and IL-6 blockade." (PMID 38138958, 2023). "IL-6 plays an important role in regulating the downstream inflammatory responses that contribute to the development of atherosclerosis." (PMID 35402550, 2022). "Combining these functions, IL-6 appears to play an important pro-atherogenic role throughout all stages of atherosclerosis, including thrombus formation and arterial occlusion." (PMID 36319844, 2022). "IL-6 has been shown to increase the secretion of adhesion molecules in ECs and exacerbate atherosclerosis in mice." (PMID 35805077, 2022).
atherosclerosis (continued). "Among pharmacological candidates, agents impacting interleukin (IL)-6 signaling have attracted attention due to converging evidence supporting the relevance of IL-6 in atherosclerosis." (PMID 35948913, 2022). "In the current study, the mean values of CRP and IL-6 were significantly elevated in obese, obese with atherosclerosis compared with control group." (PMID 36407366, 2022). "Interleukin-6 (IL-6) is an acute-phase protein that plays a significant role in the inflammatory response, vascular inflammation, and atherosclerosis process." (PMID 36028849, 2022). "Of note, therapeutic strategies targeting inflammation, including IL-6 blockers, are being studied for their potential role in avoiding atherosclerosis." (PMID 35683507, 2022). "miR-652-3p is highly expressed in atherosclerosis, miR-652-3p inhibitor decreased IL-1β, IL-6, and TNF-α expression after ox-LDL treatment." (PMID 36248191, 2022). "Recent study has found that the diabetic patients have increased blood levels of IL-6, which is known toincrease the inflammation and development of vascular disease and atherosclerosis." (PMID 37323554, 2022). "The pleiotropic cytokine IL-6 plays a key role in numerous pathological processes, such as atherosclerosis and rheumatic diseases, which exhibits both pro- and anti-inflammatory properties depending on the targeted cell type." (PMID 35459215, 2022). "Among other cytokines, IL-6 is considered an orchestrator of the inflammatory response and a key player in atherosclerosis in humans." (PMID 35887619, 2022). "In sum, these data indicate that, in mice with atherosclerosis, endothelial IL-6 production augments HSPC proliferation and leukocytosis and, more generally, that endothelial cell interactions with HSPCs are pathologically altered in atherosclerosis." (PMID 35747128, 2022). "Additionally another study examined into whether hypertension could raise the risk of atherosclerosis by causing pro-inflammatory effects by investigating the relationship between blood pressure with baseline plasma concentrationsof IL-6 and found a strong correlation between IL-6 levels (P=0.001)." (PMID 37323554, 2022). "IL-6 levels are increased in cardiovascular disease, including atherosclerosis and hypertension, where it is thought to promote alterations in vascular function and structure." (PMID 35740044, 2022). "TET3 increases IL6 expression by up-regulation of 5hmC in IL6 promoter in chronic hypoxia induced atherosclerosis in offspring rats." (PMID 36070294, 2022). "There is evidence that with increased PM2.5 exposure, various inflammatory markers and immune parameters associated with atherosclerosis are reported to be elevated, including high-sensitivity CRP, plasma fibrinogen, IL-6, immunoglobulin (Ig)G, IgM, and IgE." (PMID 36082127, 2022). "IL-6 has a variety of functions, making it a key player in the inflammatory response, also in different stages of atherosclerosis." (PMID 36319844, 2022). "Pro-inflammatory cytokines IL-1β, IL-6, and TNFα, released into systemic circulation during active RA, are considered to be the main contributors to atherosclerosis due to their impact on lipid and lipoprotein metabolism, and the biology of the artery wall." (PMID 36297390, 2022). "Atherosclerosis is known to be a chronic inflammatory process in which interleukin 6 (IL-6), myeloperoxidase (MPO), matrix metalloproteinase 9 (MMP-9), and intercellular and vascular cell adhesion molecules are used as biomarkers." (PMID 35563387, 2022). "Meantime, the expression of pro-inflammatory factors, including intercellular adhesion molecule-1 (ICAM-1), vascular cell adhesion molecule-1 (VCAM-1), and interleukin-6 (IL-6) were increased, which led to vascular endothelial injury and atherosclerosis." (PMID 35935626, 2022). "For our analysis, we chose three cytokines that lead in the processes of atherosclerosis: interleukin 6 (IL-6), interleukin 18 (IL-18) and tumor necrosis factor α (TNF-α)." (PMID 35630041, 2022).
atherosclerosis (continued). "In plasma of SLE patients, increased concentrations of IL-6 and monocyte chemoattractant protein-1 (MCP-1), cytokines associated with adverse lipid profile and atherosclerosis, were detected." (PMID 36297390, 2022). "In the final stages of atherosclerosis, including atherothrombosis, IL-6 induces aggregation and activation of platelets and thereby accelerates thrombus formation." (PMID 36319844, 2022). "On the one hand, experimental atherosclerosis studies show that treatment with recombinant IL-6 (rIL-6) promotes early atherosclerosis in C57Bl/6 and ApoE-deficient mice." (PMID 35402550, 2022). "In later stages of atherosclerosis, growth and progression of atherosclerotic lesions are promoted by IL-6 through induction of platelet-derived growth factor (PDGF) which causes growth of vascular smooth muscle cells." (PMID 36319844, 2022). "Targeting IL-1β-IL6-CRP axis with Canakinumab significantly prevents atherosclerosis-related cardiovascular events in multi-center clinical trial." (PMID 35328023, 2022). "Hyperlipidemia is a major risk factor for atherosclerosis, and the levels of pro-inflammatory cytokines, such as TNF-α, IL-1β, and IL-6, are usually increased and play a vital role during the early progression of atherosclerotic plaques." (PMID 36500975, 2022). "Some studies have highlighted that during chronic infections and inflammation, elevated levels of the pro-inflammatory cytokines interleukin (IL)-6 and C-reactive protein (CRP) are associated with subclinical atherosclerosis." (PMID 35819948, 2022). "Atherosclerosis and the build-up of fatty streak and plaques are accelerated by aberrant levels of IL-6 and IL-10." (PMID 36139806, 2022). "A significant role of IL6 in the pathophysiology of atherosclerosis has also been suggested, and atherosclerosis even has been suggested to be an inflammatory disease." (PMID 35990352, 2022). "The levels of inflammatory markers (IL-6, C-reactive protein, and TNF-alpha) are determined along with antibody titers to three latent viruses associated with atherosclerosis." (PMID 35911274, 2022). "From a cardiovascular perspective, CHIP is associated with accelerated atherosclerosis, as genes encoded by CHIP are also involved in de-activation of interleukin-6 (IL-6), ultimately leading to increased circulating levels of IL-6 and increased inflammation." (PMID 36158986, 2022). "These proinflammatory cytokines are involved in accelerating atherosclerosis progression; for example, IL-6 promotes cell adhesion and high fat-induced atherosclerosis." (PMID 35137664, 2022). "Rising plasma levels of TNF-α is associated with IL-6 and CRP in elderly people as well; TNF-α is correlated to atherosclerosis and Alzheimer’s in people over 100 years old78." (PMID 36496428, 2022). "A previous study reported the link between the gene deletion of EGFR and the reduction in IL-6 and TNFα in myeloid cells, which attenuates atherosclerosis." (PMID 35877429, 2022). "Enhanced production of IL6 and IL-1β by macrophages are key to augment inflammatory signaling, contributing to atherosclerosis acceleration." (PMID 35328023, 2022). "Atherosclerosis is a complex process that entails inflammatory pathways and promotes the production of proinflammatory cytokines such as interleukin 6 (IL-6)." (PMID 36397128, 2022). "In atherosclerosis, it exerts its protective effects via inhibition of inflammation (suppression of IL-1, IL-6, and TNF-α), oxidative stress, endothelial monocyte adhesion, and lesional foam cell apoptosis." (PMID 36555579, 2022). "Pro-inflammatory cytokines, such as IL-1β, IL-6, and TNF-α play important roles in atherosclerosis progression and are associated with adipokines." (PMID 35566578, 2022). "The role of (Il-6) in the development of atherosclerosis has been widely described in InCHIANTI and MESA studies as an independent predictor of peripheral arterial disease (PAD) in community screening, irrespective of ethnicity." (PMID 35630041, 2022).
atherosclerosis (continued). "IL-6 has been shown to be involved in inflammatory processes and in the development and progression of atherosclerosis." (PMID 35847417, 2022). "Monocytes of patients with atherosclerosis showed a higher glycolytic rate and an increased mRNA expression of IL-6 and IL-1β compared to healthy controls." (PMID 35935635, 2022). "It has been reported that interleukin-6 gene is related to the development of cardiovascular diseases such as atherosclerosis and coronary artery disease.This was due to the large variability and short half-life of interleukin 6 (IL-6)." (PMID 36518119, 2022). "Elevated levels of CRP, IL-1β, IL-6 and TNF-α in patients with chronic inflammatory diseases stimulate the initiation and accelerate the progression of atherosclerosis, increasing markedly risk of CVD events." (PMID 36297390, 2022). "Nrf2 depletion in macrophages leads to increased foam cell formation, increases the M1 inflammatory phenotype with enhanced expression of pro-inflammatory monocyte chemoattractant protein-1 and interleukin-6, and aggravates atherosclerosis." (PMID 36386929, 2022). "In conclusion, the results suggest that Mettl14 can regulate the function of macrophages in atherosclerosis via Myd88/IL-6 in vivo." (PMID 35598196, 2022). "This trend was complementary to plasma IL-6 and IL-10 levels, supporting the relationship between cytokines and atherosclerosis progression." (PMID 36139806, 2022). "A competitive bone marrow-transplantation assay comparing Cdh5CreERT2;Il6fl/fl to Cdh5CreERT2 bone marrow obtained from mice with atherosclerosis revealed a lower blood leukocyte chimerism for cells originating from donors with endothelial deletion of Il6." (PMID 35747128, 2022). "Inhibiting IL-6/STAT3 signaling pathway can protect against high-fat-induced atherosclerosis in ApoE (-/-) mice." (PMID 35783840, 2022). "During early Angiotensin II-induced atherosclerosis, IL-6, produced by activated macrophages and fibroblasts in the aortic adventitia, can induce the JAK-STAT3 pathway." (PMID 36299596, 2022). "It has been reported that reducing the production of IL6 mediated by ROS/p38//NF-κB signaling pathway can attenuate atherosclerosis." (PMID 35783840, 2022). "Hence, whether targeting IL-6, downstream of IL-1 and IL-18, might quell inflammation with less impairment of host defenses, especially since IL-6 is causally involved in atherosclerosis, as shown by Mendelian randomization analysis, is an ongoing issue that warrants further investigation." (PMID 36082127, 2022). "A previous study showed that PN saponins from PN can suppress atherosclerosis, reduce NF-κB signaling activation and inhibit proinflammatory factors, including IL-6, IL-1β, TNF-α, and Calpain1 protein expression." (PMID 36501304, 2022). "IL-6 holds a dominant role in the acute phase of inflammatory response, participates in the development of atherosclerosis, and constitutes a strong prognostic mortality marker along with hs-CRP and fibrinogen." (PMID 36010052, 2022). "The pro-inflammatory cytokines TNF-α and IL-6 play crucial roles in inflammation and exacerbate atherosclerosis in murine species." (PMID 35625895, 2022). "Well-known inflammatory markers, hs-CRP and IL-6 were also upregulated during atherosclerosis progression." (PMID 36428896, 2022). "One prospective study showed that increased IL-6 significantly increased the risk of future CAD and played a crucial part in early atherosclerosis." (PMID 36243997, 2022). "It is roughly understood that inflammation linked with the hyperactivation of cytokines, such as IL-1β, IL-6, IL-10, and TNF-α causes pathogenesis of coronary heart disease and atherosclerosis." (PMID 36289895, 2022). "It has also been suggested that zinc deficiency is negatively correlated with IL-6, promoting inflammation, T2DM, and atherosclerosis." (PMID 34836405, 2021).
atherosclerosis (continued). "Interleukin-6 (IL-6) is an upstream inflammatory factor that plays a critical role as a mediator in propagating the inflammatory response and atherosclerosis progression." (PMID 33927687, 2021). "Inflammatory markers, including CRP, IL-6, and Pentraxin-3, are used to monitor the atherosclerosis process in coronary artery disease." (PMID 33613306, 2021). "Elevated ox-LDL levels are reported to be strongly positively linked to both atherosclerosis and inflammatory markers, including CRP, TNF-α and IL-6." (PMID 33670720, 2021). "IL-6 is considered a biomarker in the development of atherosclerosis and progression of inflammation in atherosclerotic vessels." (PMID 33669285, 2021). "In conclusion, this study showed that GDF-15 suppressed atherosclerosis by inhibiting lipid accumulation and decreasing the expressions of IL-6, IL-8, MCP-1, and MMP-9 in macrophages." (PMID 34539804, 2021). "Yet, hepatocyte selective deletion of gp130, which should mute putatively anti-inflammatory classical IL-6 signaling, reduces atherosclerosis." (PMID 33924019, 2021). "In the general population, higher plasma IL-6 levels have been associated with greater carotid IMT, atherosclerosis progression, coronary heart disease and CV deaths." (PMID 34640478, 2021). "This review will focus heavily on IL-6, a cytokine with a complex signaling pattern, because it is becoming clinically actionable as a target in atherosclerosis therapy." (PMID 33924019, 2021). "IL-6 is generally recognized as a pro-inflammatory cytokine, but it also plays a role in lowering pro-inflammatory activity by releasing soluble TNF receptors; therefore, the balance of IL-6 activity is critical in the pathogenesis of atherosclerosis." (PMID 34071276, 2021). "LTB4 then goes on to induce overexpression of TNF-α and IL-6, thereby contributing to the development of an inflammatory environment in ailments such as atherosclerosis." (PMID 33878031, 2021). "It is widely accepted that VSMCs undergo phenotypic modulation during the progression of atherosclerosis, and the contractile phenotype of VSMCs converts to the synthetic phenotype, which triggers release of many pro-inflammatory factors, such as IL-6." (PMID 34262908, 2021). "What is more, there is an established connection between IL-6 levels and endothelial dysfunction and subclinical atherosclerosis, and there are reports from multiple studies indicating that IL-6 signaling plays a role in atherothrombosis." (PMID 34356982, 2021). "The increased expression of interleukin-6 is closely related to atherosclerosis, myocardial infarction, heart failure and ischemic stroke." (PMID 34504432, 2021). "Recombinant IL-6 treatment exacerbates atherosclerosis in wild-type and atherosclerosis-prone ApoE−/− mice fed with a high-fat diet, which shows a dramatically increased lesion size." (PMID 34539804, 2021). "Dapagliflozin also suppressed iNOS, TNF-α, IL-1β, and IL-6 mRNA expression by attenuating the NF-κB transcription factor in diet-induced atherosclerosis in rat aortic arteries." (PMID 34124273, 2021). "The contemporary theory of the inflammatory-immunological pathomechanism of atherosclerosis includes the participation of interleukin-1β (Il), Il-6, Il-10, Il-12, RANTES, and homocysteine in this process." (PMID 34771080, 2021). "Proinflammatory cytokines including TNF-α, IL-1β, IL-6 are also a mediator of atherosclerosis since they activate endothelial cells, attract monocytes, and facilitate their adhesion by up-regulating MCP-1, ICAM, VCAM." (PMID 34885795, 2021). "Baseline characteristics of patients according to atherosclerosis vascular beds involvement numbers and IL-6 level." (PMID 33927687, 2021). "As a result of several studies commonly showing the relationship between IL-6 and atherosclerosis, IL-6 became a therapeutic target for atherosclerosis." (PMID 34071276, 2021).